IFNG (interferon gamma)
Diseases named in the same sentence as IFNG in open-access papers (continued):
Sharing a sentence is not in itself a finding about the gene and the disease.
tumor (continued). "The sensitivity of tumor cell-cycle arrest to IFNG is determined by the parameter ki." (PMID 37182110, 2023). "Bifidobacterium can directly induce DC maturation and cytokine (IFNγ, TNFα, IL-10, IL-17) production, thus promoting anti-tumor immunity and anti-PD-L1 efficacy and almost inhibiting tumor progression after combination therapy with PD-L1 monoclonal antibody (mAb)." (PMID 37841431, 2023). "Therefore, we presumed an opportunity for targeting IFNγ to improve vascular function and promote drug delivery for tumour chemotherapy." (PMID 37056922, 2023). "In addition, it has been shown that YB1 administration can induce IFNγ secretion and activate NK cells to eliminate tumor cells." (PMID 38020179, 2023). "Crosstalk between dendritic cells and NK cells occurs through the release of biochemical signals such as cytokines, chemokines, and interferon-gamma.94-98 Tumor antigens picked up by dendritic cells are presented to T cells that can perpetuate an adaptive immune response." (PMID 37774394, 2023). "IFNγ has a complex paradoxical relationship with both pro- and anti-tumor effects." (PMID 38130991, 2023). "Notably, the tumor cell subset that converts to an intermediate E/M state in response to IFNγ (12%) has a higher PD-L1 expression than cells remaining epithelial." (PMID 37638024, 2023). "Similarly, tumors from patients with better survival were also enriched in genes related to cell cycle regulation and cell division, but crucially, also in processes related to anti-tumor immunity: interferon gamma production and innate immunity." (PMID 36675137, 2023). "In a pilot trial where two patients with synovial sarcoma were treated with an addition of IFNγ and IL-2 to the combined cyclophosphamide and adoptive T cell transfer therapy, although one patient showed significant tumour regression, the other suffered fatal histiocytic myocarditis." (PMID 37455828, 2023). "Furthermore, immunotherapy-activated CD8+ T cells induces the ferroptosis of tumor cells by secreting interferon gamma (IFN-γ) and inhibiting system Xc- on the cell membrane." (PMID 37325669, 2023). "IFNγ regulates immune responses against intracellular microorganisms and controls tumor immunity." (PMID 37885900, 2023). "Interestingly, depletion of ICBs and Tregs promotes vascular normalization by reducing tumor vascular density and reactivating IFNγ producers (i.e., CD8+/CD4+ effector T cells), which IFNγ has the potential to limit tumor angiogenesis." (PMID 37727791, 2023). "It is possible that a sub-neutralizing dose of anti-IFNγ might dampen the pro-tumor effects of IFNγ signaling while preserving anti-tumor immunity." (PMID 38130991, 2023). "Among the pro-tumor effects, IFNG can lead to recruitment of suppressive cells like regulatory T cells or myeloid-derived suppressor cells (MDSCs) or induce expression of immune checkpoint ligands like programmed death-ligand 1CD274 (common alias: PD-L1, encoded by the Cd274 gene) on tumor cells." (PMID 37182110, 2023). "Indeed, prolonged IFNγ signaling has been shown to result in tumor progression through the upregulation of inhibitory ligands and receptors, immune cell exhaustion and resistance to immunotherapy." (PMID 36980678, 2023). "Several therapeutic strategies that target one or more of the major biological pathways, including the IFNγ pathway, other immunological checkpoints, the tumor microenvironment, and epigenetic modification, have been developed to combat acquired resistance to ICIs." (PMID 37038154, 2023). "Interestingly, we found that IFNγ blockade was the only depletion that significantly altered tumor growth and overall survival." (PMID 36881506, 2023). "Moreover, the interaction between tumor‐infiltrating T cells, IFNγ signaling genes, and PD‐L1 expression suggests that activated T cells contribute to high levels of PD‐L1." (PMID 36177552, 2023).
tumor (continued). "The CT26 tumor model is known to be immunogenic and responsive to immunotherapy, and our results suggest that anti-IFNγ PET may be able to detect localized pre-treatment IFNγ expression." (PMID 38130991, 2023). "Furthermore, co-culture of PD-1high hHER2-CAR-T cells with hHER2-B16 or hHER2-E0771 upregulated ICAM-1 expression on the target tumor cells to a level similar to that on B16 cells treated with recombinant IFNγ alone." (PMID 37388744, 2023). "Primary tumor weights were smaller in Cxcr3−/− vs. Cxcr3+/+ relapsed mice, indicating increased tumor dissemination in Cxcr3−/− mice was not merely due to larger primary tumors and consistent with increased T cell IFNγ production at the earlier timepoint." (PMID 36472588, 2023). "CXCL10 is a chemokine that attracts T cells to tumor sites and is induced by IFNγ and Type I IFNs." (PMID 37404831, 2023). "However, M1 macrophages act as a subset of TAMs present in ascites, promoting the expression of interferon-gamma (IFN-γ) to induce cytotoxicity against tumor cells by Interleukin-12 (IL-12)." (PMID 37039909, 2023). "The immunomodulatory effect of Dt on PC3 and DU145 tumor cells is elicited by the inhibition of the release of the pro-lymphangiogenic interleukins and macrophage stimulating factors as well as interferon gamma (IFN-γ) in DU145 cells." (PMID 36829917, 2023). "Unlike splenocytes from nelatimotide-only Emulsion-treated mice, splenocytes from DSP-7888 Emulsion-treated mice exhibited high levels of interferon-gamma secretion, including when co-cultured with tumor cells; interferon-gamma secretion was further enhanced by concomitant treatment with anti-PD-1." (PMID 36138335, 2023). "PD-1 inhibition promotes tumor cell ferroptosis through interferon-gamma." (PMID 37252189, 2023). "Although the numbers are small, we noted that PD1 PROG cells with intrinsic IFNγ activity were derived from tumor biopsies with a trend toward lower CD45+ cell content (3/5 tumor dissociates with <10% CD45+ cells) and high macrophage content (2/5 dissociates with >35% macrophages)." (PMID 36934113, 2023). "Interestingly, the effector (IFNγ-producing) CD8 circulatory T cells were significantly lower in the tumor-bearing recTLT-1 mice than in the tumor-bearing vehicle group." (PMID 36305874, 2023). "In addition, IFNγ is necessary to stimulate tumor-specific NOS2/COX2 expression, which through a multifaceted process, also drives oncogenic pathways and shapes immunological profiles associated with poor prognosis." (PMID 37169743, 2023). "Moreover, in a separate study, we showed that IFNγ plays a role in transformation of tumor phenotype." (PMID 38085642, 2023). "Together, these results yielded a conceptual model whereby IDO1 acts as a regulatory node at the interface between IFNγ and IL6, shifting the inflammatory microenvironment to a tumor-promoting state by preventing the ability of IFNγ to pare back the tumor neovasculature." (PMID 37182174, 2023). "Moreover, CAR-147 macrophages have shown an antitumor effect by increasing IL-12 and IFNγ levels in tumor tissue." (PMID 36900394, 2023). "CD8+ T lymphocytes may release IFNγ to upregulate PD-1/PD-L1 and IDO1 gene expression, with IDO1 overexpression linked to poor prognosis, tumour development, and metastasis." (PMID 37760841, 2023). "Although athymic nude mice lack a thymus and are unable to produce T cells, large quantities of IFNγ are still secreted by the present NK cells and other remaining immune cells, which might robustly stimulate PD-L1 expression in tumour cells." (PMID 37370741, 2023). "Effector T cell infiltration is enhanced in tumours derived from cells pre-treated with IFNγ in immunocompetent female mice when PARP14 is pharmacologically inhibited or knocked down, while the presence of regulatory T cells is decreased, leading to restoration of α-PD-1 sensitivity." (PMID 37752135, 2023).
tumor (continued). "We hypothesized that interferon gamma (IFNγ) regulates NAMPT in tumor cells as a mechanism of resistance that impedes the normal anti-tumorigenic effects of IFNγ." (PMID 36900204, 2023). "In summary, our conclusions from the present study are that RHAMM contributes to primary tumor and metastasis clonal heterogeneity by regulating tumor cell survival via STING/IFNG/STAT1 signaling in microenvironments characterized by a high potential for DNA damage." (PMID 37349798, 2023). "To understand whether IFNγ sensing by CD8 T cells directly affected the efficacy of anti-tumor responses, we used a mouse model whereby IFNγ sensing was ablated in CD8 T cells by deleting IFNγR1 specifically in mature CD8 T cells (CD8-IFNγRKO)." (PMID 36658158, 2023). "Moreover, IFNG induces increased antigen presentation on tumor cells, which should lead to increased stimulation of CTLs via their T cell receptors." (PMID 37182110, 2023). "However, only CISP resulted in the strongest increase of CD8 T cells, NK cells, M1 macrophage and anti-tumor cytokines including IL-6, IFNγ, IFNβ, TNFα and IFNα in LLC tumors." (PMID 37607938, 2023). "Interferon gamma response genes were induced post-treatment and cell adhesion genes were repressed, although the association of these observations with tumor response and clinical outcomes was not statistically powered due to limited samples available." (PMID 37507657, 2023). "Type 1 and Type 2 immunity are two major types of immune responses, type 1 immunity is characterized by the activation of T helper 1 (TH1) cells and the production of cytokines such as interferon-gamma (IFN-γ), which are important for the elimination of intracellular pathogens and tumor cells." (PMID 37925492, 2023). "Because these transitions could in turn affect PD-L1 expression, inhibiting further IFNγ production, bystander tumor cells might indirectly be protected by EMT of a tumor subpopulation." (PMID 37638024, 2023). "We hypothesize that this change in the ratio of IFNγ to IL10 in the cytotoxic Tr1-like cells plays a key role in their anti-tumor role in the presence of PD1 blockade." (PMID 37654482, 2023). "The LRisk group was characterized by immune-active signaling pathways (interferon-gamma, T cell activation, etc.)and higher proportions of anti-tumor immune cells (NK, M1, etc.)while HRisk patients were associated with higher stromal scores and less TCR richness." (PMID 37179119, 2023). "Moreover, we observed proliferation of T cells featuring Ki67 expression and enhanced anti‐tumor immunity featuring perforin and IFNG upregulation within the TIME after ICB treatment, especially in the anti‐TIGIT group." (PMID 36725337, 2023). "IFNγ may increase the PD-L1 expression on tumor cells, thus the rationale of our work was to combine L19-IFNγ KRG with anti-PD1 and anti-PD-L1 antibodies." (PMID 36839699, 2023). "Third-generation EpCAM-CAR-T cells were cytotoxic to target cells and induced lysis in them in an EPCAM-dependent manner leading to notable regression of tumor growth and secretion of cytotoxic interferon gamma (IFN-γ) and tumor necrosis factor alpha (TNF-α) in the MDA-MB-231 model." (PMID 37457288, 2023). "Ultimately, this “pre-CAR-T” IFNγ exposure and subsequent Qa-1b induction may protect tumor cells from CAR-T therapy in vivo, a phenomenon that cannot be captured in vitro unless the in vivo environment is mimicked by pre-treating tumor cells with IFNγ." (PMID 38052854, 2023). "Thus, our best-fitting parameters implied that cycling tumor cells are sensitive to IFNG even at low expression levels." (PMID 37182110, 2023). "Moreover, the frequencies of CD4+ and CD8+ T cells were significantly up-regulated in the tumor tissues, with substantial increases in IFNγ, TNFα and IL-17A expression in CD8+ T cells and augmented IL-17A expression in CD4+ T cells." (PMID 38074634, 2023). "Anti-IFNγ combined with anti-PD-1 therapy and chemotherapy might promote anti-tumor effects further." (PMID 37056922, 2023).
tumor (continued). "Tumor volume, the frequency and phenotypes of WT1-specific CTLs in CD8+ T cells in peripheral blood (PB) and tumor-infiltrating lymphocytes (TILs), as well as the proportion of interferon-gamma (INF-γ)-producing CD3+CD4+ T cells pulsed with WT135–52 peptide in splenocytes and TILs were determined." (PMID 36803483, 2023). "Even more importantly, we could confirm the ability of T lymphocytes to produce IFNγ and TNFα, cytokines that are essential in the process of recognition and anti-tumor cytotoxic capacity." (PMID 37173879, 2023). "To understand whether IFNγ acted preliminarily in LN or at the tumor site, we performed Differential Gene Expression analysis between control and CD8-IFNγRKO cells from LN and tumors." (PMID 36658158, 2023). "This was indicative of the role of IFNG in regulating anti-tumor immunity." (PMID 37408777, 2023). "They observed an IFNγ-depended intra-tumoral influx of cytotoxic T cells, T helper cells and monocytes following low-dose radiation of 1Gy that can be combined with immunotherapy for a synergistic effect toward tumor regression." (PMID 37006319, 2023). "However, chronic exposure of tumour cells to IFNγ limits the effectiveness of immune checkpoint inhibitors such as α-PD-1, driving resistance to treatment." (PMID 37752135, 2023). "This suggests that AA found in the tumor microenvironment could potentially be used together with IFNγ as a physiological inducer of ferroptosis." (PMID 37840106, 2023). "In addition, tumor-infiltrating immune cells, such as interferon-gamma-producing T cells, can induce PD-L1 expression in cancer cells through a positive feedback loop." (PMID 38136250, 2023). "Tumor-associated T cells, CD8 + T cells, and NK cells were significantly increased in D374Y tumors along with upregulations of multiple immune checkpoints, IFNγ, and 143 genes associated with T cell dysfunction." (PMID 36588164, 2023). "Administering therapeutic agents that target tumour-intrinsic cell death signalling could lower the cytotoxic threshold of tumour cells to TNF and IFNγ, increasing their susceptibility to immune attack." (PMID 37752135, 2023). "Due to the early reduction in IFNG signaling, it is unclear whether IFNG can be entirely responsible for the G1-phase tumor cell-cycle arrest, which followed highly similar dynamics to the CTLs." (PMID 37182110, 2023). "The biomarkers of ICB resistance may include PD-L1 positivity on tumor and immune cells, an IFNγ gene signature, and the level of IFN signaling that exists within cancerous cells." (PMID 37304294, 2023). "At the later step of tumor progression, IFNγ impairs secondary anti-tumor immune responses." (PMID 37190141, 2023). "IFNγ is an important modulator of tumour vascular functions 17-19." (PMID 37056922, 2023). "In support of this conclusion, we found a significant increase in pro-inflammatory cytokines, such as IFNγ and IL-6, at the later stages of tumor growth compared to early stages in HFD-fed mice, correlating with the increased tumor size in HFD-fed mice at 5 wpi." (PMID 36675341, 2023). "Detecting excess AA in the tumor microenvironment suggests that AA + IFNγ derived from CD8+ T cells may be the first identified natural ferroptosis trigger." (PMID 38127902, 2023). "It is well recognized that CTLs are able to produce large amounts of interferon-gamma (IFNg), which may directly inhibit tumor growth, especially of IFNg-receptor-expressing cells." (PMID 37515143, 2023). "An improved prediction of RFS was accomplished when the ctDNA level was combined with other biomarkers from the tumor microenvironment such as CD8+ T-cells, PD-L1, interferon-gamma (IFN-g) gene expression signature and tumor mutational burden (TMB), but also Breslow level and clinical stage." (PMID 37444558, 2023).
tumor (continued). "In OSM-knockout mice, cSCC tumor volume was reduced by approximately 30% when compared to wild-type mice after one month, however there were still significant amounts of IL-6, IL-1β, IL-23α, CXCL1, IL-4, and IFNγ present in the tumor tissue compared to normal skin." (PMID 37841259, 2023). "Song and colleagues postulated that the effect of IFNγ on tumor cells is strictly dose-dependent." (PMID 36839699, 2023). "IFNγ could promote tumor immune escape by regulating the PD-L1 expression via the JAK/STAT and PI3K-AKT signaling pathways." (PMID 37182129, 2023). "CTLA-4 blockade could induce an abscopal effect on metastatic lesions, when primary tumors were locally irradiated, with the effect showing a correlation with the frequency of tumor-specific IFNγ-secreting CD8 T cells." (PMID 36831435, 2023). "Either pathway could be compensatory when the flow of IFNγ to tumor or host cells was disrupted by IFNγ-sensing defects." (PMID 36881506, 2023). "Besides these effects, IFNγ directly inhibits tumor cell growth through antiproliferative and proapoptotic activity." (PMID 37803324, 2023). "IFNγ leads to an increase in the expression of PD-L1/2 in the tumor and in the tumor infiltrate." (PMID 36946842, 2023). "As a second step, we extended our analysis and modeling to integrate the dynamics of various exhaustion markers as potential explanation for the short window of IFNG production, with CTLs losing the ability to produce IFNG within days of CTLs infiltrating the tumor." (PMID 37182110, 2023). "Furthermore, GPR68 functionally inhibits the expression of IFNγ in the tumor infiltrating CD8+ T cells and NK cells as well as the inflammatory cytokine expression in the spleen in male mice but not in females." (PMID 37350933, 2023). "Furthermore, in a melanoma mouse model, IFNγ and AA, one of the PUFAs, have been identified as an anti-tumor combination." (PMID 37840106, 2023). "However, mice that received CD4 T cells from ITI-3000-immunized IFNγ-/- mice showed tumor kinetics and overall survival equivalent to that of mice that received CD4 T cells from control-immunized mice." (PMID 37711623, 2023). "Critically, immunotherapeutic treatment with IFNγ must be carefully designed to maximise efficacy and to prevent iatrogenic harm through tumour induction, especially as all upcoming and ongoing clinical trials continue to utilise IFNγ as a potential treatment agent for cancer." (PMID 37455828, 2023). "Mechanistically, IFNγ induces the expression of cytokines IL-1β, IL-6, IL-12, IL-18, IL-23, TNFα, and proinflammatory factors such as ROS and NO by M1 macrophages, thereby contributing to M1 macrophage-mediated anti-tumour immunity." (PMID 37455828, 2023). "CD8+ T cells downregulate the expression of SLC3A2 and SLC7A11, two subunits of the glutamate–cystine reverse transport system Xc-, by releasing IFNγ, which in turn impairs cystine uptake by tumor cells, promoting tumor cell lipid peroxidation and the onset of ferroptosis." (PMID 36671532, 2023). "Moreover, triple therapy with T-cell inducting vaccine, PD-1 blockade, and CD40 agonist significantly promoted anti-tumor T cell immunity, marked by elevated infiltration of IFNγ-, TNFα-, and granzyme B-secreting effector T cells." (PMID 37771596, 2023). "Conversely, tumours can also produce tumour necrosis factor-alpha, interferon-gamma, interleukin-10 and interleukin-12, which may decrease lymphocytic activity as they are immunosuppressive molecules." (PMID 37046847, 2023). "Furthermore, changes in either cellular metabolism or epigenetic activities reportedly contribute to downregulation of MHC‐I molecules or reduced tumor cell responsiveness to IFNγ." (PMID 37452654, 2023). "For example, NK cells can be recruited by C-X-C motif chemokine ligand 9 (CXCL9), produced in activated CD103+DCs (dendritic cells), into the tumor microenvironment to express granzyme B, interferon-gamma (IFN-γ), and tumor necrosis factor-alpha (TNF-α) to kill HCC cells." (PMID 37239062, 2023).